IL6 (interleukin 6)
Diseases named in the same sentence as IL6 in open-access papers (continued):
Sharing a sentence is not in itself a finding about the gene and the disease.
tumor (continued). "In this regard, the in vitro data suggest that the free bacteria or the infected tumor cells present into the TME are capable to stimulate the activation of macrophages and the release of cytokines and chemokines (TNF-α, IL-6, IL-12, and CXCL10) in a MyD88-dependent manner." (PMID 38835781, 2024). "Notably, IL-6 can elevate the levels of EIF4A3 and CCL2 in tumor cells via activation of the JAK2/STAT3 pathway, further facilitating tumor cSERPINE2 biogenesis and inducing TAMs recruitment." (PMID 38397395, 2024). "However, in the off-tumor condition, the concentrations of IFN-γ, IL-6, and TNF-α released from MB2033-treated hPBMCs were lower (data not shown) than those released following the treatment of aldesleukin or αPD-L1 × non-α IL-2v." (PMID 38834889, 2024). "Inflammatory cytokines like TNF-α and IL-6 serve as a conduit for this communication and contribute to the recruitment of more inflammatory cells into the TME, increasing the growth and survival of genetically modified tumor cells." (PMID 38803729, 2024). "Furthermore, IL-6 was recently shown to be over-expressed in TSC2-disease models, and inhibition with IL-6 antibody antagonists was shown to reduce tumour growth." (PMID 39070657, 2024). "However, in the 4T1 highly aggressive tumor model, it was insufficient to reverse MDSC-mediated immunosuppression because of the IL-6 signaling pathway in MDSCs." (PMID 37108179, 2023). "CAF-derived interleukin-6 (IL-6) activation of the Janus kinase (JAK)-signal transducer and activator of transcription (STAT) (JAK-STAT) signaling pathway leads to increased TGF-β signaling, promoting tumor growth and metastasis." (PMID 36672326, 2023). "Interestingly, CX-4945 treatment lowered HMGB1, β-catenin, C-MYC, phosphor-MAX, IL-6, and CSNK2A1 protein levels in tumor tissues in CX-4945 treatment as compared with a vehicle." (PMID 37347224, 2023). "Upregulated IL-6 can boost the proliferation of CAFs and ESCC cells by upregulating PSTAT3 and PERK 1/2 expression and downregulating caspase-3 cleavage, resulting in decreased apoptosis and increased tumour growth and invasion." (PMID 37927475, 2023). "CRS occurs when tumor-activated CAR T cells stimulate bystander immune cells, primarily myeloid cells, to release massive amounts of proinflammatory cytokines, particularly IL-6." (PMID 37947658, 2023). "Interestingly, not only M2 but M1-TAMs are also reported to secrete IL6 and IL12, which nudge the tumor cells towards CSC phenotype." (PMID 38035101, 2023). "M1 macrophages exhibit anti-tumor activity and primarily inhibit tumor growth and metastasis by producing inflammatory mediators and cytokines, such as tumor necrosis factor-alpha (TNF-α), interleukin-12 (IL-12), and interleukin-6 (IL-6)." (PMID 38037023, 2023). "In addition, active angiogenesis of tumor upregulates the suppressive immune molecules, such as PD-L1, IL-6, IL-10, and Fas ligand, which recruit Tregs into TME and clean up cytotoxic T lymphocytes to make it difficult to kill the tumor cells." (PMID 37345194, 2023). "Although anti–CTLA-4 alone inhibited tumor growth to a greater extent than mice treated with an isotype control (P = 0.0004), blockade of IL-6 alone did not delay tumor growth." (PMID 36881480, 2023). "Furthermore, IL-6 activates MMP and forms desmoplastic tumor stroma, which acts as a barrier to avoid recognition by the immune system and subsequent T-cell infiltration." (PMID 38026978, 2023). "Additionally, L-SMI induced the accumulation of M2 macrophages, up-regulation immune checkpoint genes and proinflammatory cytokines (IL-6, IL-10, and TGF-β), and alteration the tumor microenvironment and immune status." (PMID 38074647, 2023). "It decreases the tumorigenesis marker such as matrix metallopeptidase 3 (MMP-3), interleukin-6 (IL-6), tumor necrosis factor-α (TNF-α), and proliferating cell nuclear antigen (PCNS), and stem cell markers including CD133 leading to reducing tumor size of REM134 canine mammary carcinoma." (PMID 38188673, 2023).
tumor (continued). "The elevation of interleukin 6 over-activates the Janus kinase/signal transducer and activator of transcription (JAK/STAT3) signaling pathway, which is responsible for tumor proliferation, invasion, and metastasis, in addition to suppressing the antitumor immune response." (PMID 37445794, 2023). "Also in these settings, the increased M2 phenotype triggered by the tumor cells was reverted upon SKI-II treatment, as evident by reduced expression of Arg1 and Msr1 and enhanced expression of Tnfα and Il-6." (PMID 36672428, 2023). "IL-6/JAK2/STAT3 activation is mediated by the upregulation of EMT-induced transcription factors (e.g., Snail Zeb1, JUNB and Twist-1) to induce EMT, together with enhancing tumor cell migration and motility by activating the adherent patch kinase (FAK)." (PMID 36923251, 2023). "Using multiplex immunoassays, we examined type I IFN (IFN-α, IFN-β), type II IFN (IFN-γ), proinflammatory cytokine (GM-CSF, IL-6, IL-12p70), and proinflammatory chemokine (CXCL10 [IP-10], CCL2 [MCP-1], CCL3 [MIP-1α], CCL5 [RANTES]) signaling in the tumor microenvironment (TME)." (PMID 36810257, 2023). "In tumor, liver, and spleen, IL-6 mRNA and protein expression levels were decreased by CR administration, compared to tumor-bearing mice without treatment." (PMID 37240117, 2023). "In-depth profiling of the BMSCs exosomes content in MM compared to healthy donors, demonstrated lower levels of the tumor-suppressive factor miRNA-15a, and higher levels of pro-tumoral molecules such as chemokine C-C motif ligand (CCL) 2, IL-6, and fibronectin." (PMID 38213954, 2023). "Similar to TNF-α blockade, there has been increasing interest in the use of an IL-6 inhibitor (tocilizumab) as another attractive option with proven effectiveness for treatment of irAEs without having an impact on tumor response." (PMID 37958355, 2023). "All mentioned evidence supports the present results that high IL-6-secreting CAFs were positive for CD10+ GPR77+ FAP+ which may correlate with drug resistance and may regulate anti-tumor immune responses." (PMID 37480115, 2023). "IL‐6 (involved in inflammation), INF‐γ (cytokine), urokinase (convert plasminogen into plasmin), and CCL2 (monocyte chemoattractant) were also restricted to the site of the tumor as well as decreased the process of metastasis." (PMID 38455223, 2023). "IL-6 binds with IL-6R to induce the activation of STAT3 and activated STAT3 binds to the promoter region of the VEGF gene to increase transcription, promoting the tumor angiogenesis." (PMID 37892997, 2023). "In a canine transferrable tumor model, tumor-derived TGF-β impairs DCs’ maturation, which may be reversed by IL-6 through Smad2/3 nuclear translocation interference." (PMID 37205317, 2023). "Moreover, upon antigenic activation in vitro, PB CAR-T cells released lower levels of IFN-γ, IL-6, IL-10, TNF-α, CCL2, CXCL10, and GM-CSF than Lenti CAR-T cells, but demonstrated a robust release of IL-9, indicative of a distinct anti-tumor response pathway." (PMID 37228617, 2023). "piR-823 overexpression in MM cells transmits signals to the tumor microenvironment (TME) via extracellular vesicles (EVs) to increase the expression levels of VEGF and IL-6 in endothelial cells, inducing angiogenesis and increasing tumor cells’ invasion and metastasis." (PMID 38031146, 2023). "IL-6 can also induce the production of other cytokines, such as IL-10 and transforming growth factor-beta (TGF-β), which can suppress the immune response and promote tumor growth." (PMID 37174117, 2023). "Co-culturing with BMDCs found that tumor cells after PDT could promote the maturation and activation of BMDCs and the production of IL-6." (PMID 37894410, 2023). "IL-6 released from MSCs stimulates the release of endothelin-1 (ET-1) in cancer cells, which in turn triggers the activation of Akt and ERK in endothelial cells, improving their ability to attract other cells to the tumor and promoting angiogenesis." (PMID 38022534, 2023).
tumor (continued). "Similarly, tumor cell-derived TGF-β signaling can trigger the release of several cytokines from CAFs, such as IL-6, CXCL10, and CCL5, which, in turn, drive the upregulation of glycogen metabolism in tumor cells through phosphoglucomutase 1 (PGM1) activation." (PMID 38002286, 2023). "Soluble inflammatory mediators and growth factors, such as Interleukin 6 (IL-6), IL-8 and tumor necrosis factor-α (TNF-α) are known to promote cell proliferation, inhibit apoptosis, activate survival pathways, and recruit leukocytes to the tumor site." (PMID 36823670, 2023). "The activated STAT3 pathway, in response to the binding of IL-6 secreted to its glycoprotein 130 (GP130) receptor, promotes tumour progression through the induction of various target genes involved in tumour cell survival, proliferation, angiogenesis, metastasis, and cell adhesion." (PMID 36979673, 2023). "IL-6 plays a key role in PDAC development and progression, as it affects immune suppression in the TME and enhances angiogenesis, proliferation and migration of tumour cells." (PMID 37760608, 2023). "Indeed, MSCs produced high levels of cytokines and growth factors, such as IL-6, IL-8, VEGF, FGF-β, PDGF, TGF-β, and angiopoietin, thus promoting tumor angiogenesis." (PMID 37686315, 2023). "The IL6-JAK-STAT3 signaling pathway could induce PD-1 and PD-L1 expression and promote anti-tumor immune effects." (PMID 36899891, 2023). "A mouse model confirmed that CD79A allows bone marrow-derived suppressor cells to maintain their immature state, enhances the ability to suppress T-cell proliferation, stimulates their migration, and induces the secretion of protumor cytokines such as IL-6 and CCL22, thereby promoting tumor growth." (PMID 37344840, 2023). "For instance, a study showed that co-culture of human MM cells with IL-6-releasing polymorphonuclear myeloid-derived suppressor cells (PMN-MDSCs) resulted in increased relative expression of self-renewal markers NANOG, OCT4 and SOX2 in tumour spheroids." (PMID 37808081, 2023). "Also, IL-1, IL-6, and TNF-α were evaluated as they are considered key mediator cytokines of the inflammatory milieu and modulate tumor-promoting factors." (PMID 37068081, 2023). "It appears that targeting IL-6 and/or its downstream Src-FAK signaling could suppress tumor progression though dampening the metastatic spread of tumor cells." (PMID 37047623, 2023). "Through enhancing STAT3-induced expression of IL-6, LEISA could promote tumor progression, which reveals the crucial role of LEISA in LAD." (PMID 36813772, 2023). "Finally, cytokines measurement showed, in tumor mass of αPD-L1-treated mice, an increased level of cytokines known to exert anti-tumoral actions such as TNF-α, IFN-γ, and IL-6, and a concomitant decrease of the immune-suppressive cytokine IL-10." (PMID 36854895, 2023). "Meanwhile, in our previous results, A3 could promote M1 polarization of macrophages in tumor tissues and increase the expression of the pro-inflammatory mediators TNF- α, IL-12, IL-6, and IL-1β." (PMID 36838599, 2023). "Moreover, other studies demonstrate the activation of cancer stem cells by increasing IL6 and MFG-E8 secretion stemming from overexpression of STAT3 in the tumor microenvironment." (PMID 36662090, 2023). "Chemotherapy drugs, the nature of the tumor itself, and the patient’s long-term physiological and psychological stress can lead to an increase in the production of inflammatory cytokines such as TNF-α, IL-1, and IL-6." (PMID 37375330, 2023). "The results indicated that while UBE2D3 expression did not significantly differ between tumor and normal tissues, it influenced the expression of IL6 and IL8, downstream factors of the NF-κB signaling pathway by regulating IκBa expression." (PMID 38041015, 2023).
tumor (continued). "In addition, YFJP significantly reduced the expression of inflammatory and immunosuppressive cytokines, including IL-1β, IL-6 and IL-10, while increased the expression of cellular effectors TNF-α and IFN-γ in serum and tumor tissues." (PMID 37355637, 2023). "YAP/TAZ-high tumors also secrete CCL2 and recruit TAMs to the tumor microenvironment, which then produce IL6 and GM-CSF to further amplify the accumulation of MDSCs and inhibit the activity of CD8+ T cells from generating an immunosuppressive tumor microenvironment." (PMID 37444578, 2023). "CXCL10, CXCL5, MMP1, CXCL12, CXCL11, CXCL2, STAT1, IL‐6 and TLR2 were hub genes in network and may promote or inhibit the homing or of immune cells in tumours and immune cell differentiation, bring intratumoral immune heterogeneity." (PMID 36524848, 2023). "As let-7 miRNAs including let-7a directly repress IL-6 cytokine production in breast epithelial cells, our data suggest a potential activity of XIST by repressing let-7a-2-3p in ALDH- bulk tumor cells to increase IL-6 cytokine production, which in turn promotes ALDH+ CSCs." (PMID 36922677, 2023). "Therefore, the addition of IL-6 blockers, as well as of a PD-L1 inhibitor could be useful in cancer treatment whenever previous testing for PD-L1 expression on the resident cells of a tumor has been demonstrated, so that the inhibitor will truly have an effect." (PMID 36768649, 2023). "Thus, significant upregulation was observed for multiple key cytokines, specifically IL-6, IP-10, KC, and RANTES, in the KPCA HGSOC tumor lines in response to 5-aza." (PMID 37627156, 2023). "We also confirmed that mechanical damage to the tumor, as well as the subsequent secretion of inflammatory cytokines such as IL6, did not affect the overall level of Photofrin in the tumor." (PMID 37700795, 2023). "Macrophages could promote cancer stem cells by secreting IL-6 and activating of STAT3 signaling and subsequently contribute to tumor growth." (PMID 37143953, 2023). "Although cancer‐derived EVs have been shown to contain IL‐6 the impact of EV‐delivered IL‐6 on cells within the tumour microenvironment has not been explored." (PMID 37337371, 2023). "IL-6, released by mononuclear phagocytes upon NB conditioning, and TGF-β1, produced by both immune and tumor cells, inhibit the IL-2-mediated activation of NK cells, through the activation of the STAT3 and SMAD2/3 pathways and suppression of IFN-γ, granzymes, and perforin release." (PMID 36980226, 2023). "Higher IL-6 levels and a greater number of T helper 17 (Th17) cells were observed in ICI-induced immune-related enterocolitis, and IL-6 inhibition increased the ICI-induced anti-tumor efficacy." (PMID 37208766, 2023). "The frequencies of immune cells (CD4+ T cells, CD8+ T cell, Treg cells, NK cells and CTLs) and the concentrations of cytokines (including IL-6, IL-12, Interferon (IFN)-γ, IL-10 and TGF-β) in tumour tissues were used to evaluate the immune status of the tumour microenvironment." (PMID 37076492, 2023). "In addition, IL-6 can directly stimulate the expression of VEGF and promote angiogenesis and MMPs, which play a fundamental role in tumor invasion and extracellular matrix differentiation." (PMID 37046658, 2023). "Lastly, TRPV1 agonists markedly increase IL-6 secretion in tumor-bearing mice, but not in control mice." (PMID 37371563, 2023). "Omeprazole has been proved to inhibit the activity of MAPK and NF‐κB and subside with the downregulation of TNF‐α, IL‐6 and SOD2 which may suppress the growth of tumours." (PMID 35961680, 2023). "Additionally, TAM-derived IL-6 in turn elevated CCL2 and EIF4A3 expression in tumor cells by increasing the activation of the JAK2-STAT3 pathway." (PMID 36797769, 2023). "Furthermore, treatment with C. versicolor aqueous extract resulted in significant immunomodulatory effects, which were reflected by increased IL-2, IL-6, IL-12, TNF-α, and IFN-γ production in the spleen lymphocytes of C. versicolor-treated tumor-bearing mice." (PMID 37373268, 2023).
tumor (continued). "In a mouse model, the blockade of IL-6 and PDL-1 reduced tumor progression of PDAC." (PMID 36672313, 2023). "Additionally, tumor cells and tumor-infiltrating lymphocytes produce cytokines and growth factors (e.g., TNF-α and IL6) in response to radiation and are mostly dose-dependent." (PMID 38136404, 2023). "IL-6, made from T cells, macrophages, and fibroblasts in the tumor microenvironment, stimulates signal transducer and activator of transcription 3 (STAT3) signaling that contributes to tumor progression." (PMID 37432606, 2023). "It was shown that, in HNSCC, these cells produce IL-6, which regulates OPN expression through STAT3 activation, which may promote tumor proliferation." (PMID 38003931, 2023). "We hypothesized that the efficacy of IL-6 and CTLA-4 blockade may be mediated in part by tumor-derived chemokines that enhance lymphocyte trafficking into tumors." (PMID 36881480, 2023). "In addition to direct impacts on tumor cells, IL-6 and downstream JAK/STAT3 pathway also have profound effects on tumor immunosuppressive environment." (PMID 37069669, 2023). "Factors involved in tumor-mediated NET formation include tumor-derived inflammatory and chemoattractant cytokines (IL-8, IL-6, TNF-α, G-CSF and IL-1β), tumor extracellular vesicles, tumor-activated platelets, tumor-derived HMGB1, KRAS oncogene mutation and hypoxia." (PMID 37511453, 2023). "IL-17-induced inflammatory mediators such as G-CSF, IL-6, and CXCL1 stimulate the expansion and recruitment of dysfunctional myeloid cells to establish a proangiogenic and immune-suppressive tumor environment that enhances tumor growth and metastasis." (PMID 36993955, 2023). "For instance, HFD-induced obese mice showed increases in VEGF, IL-6, chemokine ligand 2 (CCL2), and C-X-C motif chemokine ligand 1/2/13 (CXCL1/2/13), which promote angiogenesis and the infiltration of immune cells that favor tumor development and metastasis." (PMID 36670988, 2023). "Various CAF-secreted solute factors, such as IL-6, IL-33, TGF-β, stromal cell derived factor-1 (SDF-1), and CAF-derived cardiotrophin-like cytokine factor 1 (CLCF1) produce tumor-promoting signals that mediate the signal transduction of tumor cells or other cells in the TME." (PMID 37217855, 2023). "We speculate that a low level of IL-6 further diminishes STAT3 activation, thereby reducing tumor progression." (PMID 37686472, 2023). "For instance, the pro-inflammatory cytokine IL-6 stimulated the expression of Twist1 in normal fibroblasts, leading to their transdifferentiation into CAFs through STAT3 phosphorylation, thereby facilitating tumour invasion." (PMID 38173726, 2023). "Initiation of inflammation in the TME and pro-inflammatory cytokines, such as interleukin (IL)-1-β, IL-6, and IL-8, are produced by tumor cells, immune cells and nonmalignant cells that promote M1 polarization." (PMID 36816959, 2023). "In our analysis of cytokines from the 3D model supernatants, however, several critical markers of an immunosuppressive tumor microenvironment were demonstrated when culturing HDF with tumor cells (versus tumor alone), as evidenced by the upregulation of IL6, MCP-1, and SDF-1a." (PMID 37190054, 2023). "IL-6, TGF-β, IL-10 and other pro-inflammatory factors secreted by tumor cells could promote chronic inflammation by stimulating MDSCs, macrophages, and neutrophils to further secret IL-6, TGF-β, IL-10." (PMID 37644468, 2023). "Additionally, CXCL5 prompts activation of pro-tumour neutrophils via ERK and p38 signalling, resulting in elevated inflammatory cytokines like IL-6 and IL-23 that support metastatic potential of GC cells." (PMID 36932192, 2023). "Several tumor-derived molecules, such as transforming growth factor (TGFβ), fibroblast growth factor (FGF), epidermal growth factor (EGF), hedgehogs, Wnt ligands, and interleukin-6 (IL-6), act as EMT inducers." (PMID 37046817, 2023).